IL6 (interleukin 6)
Diseases named in the same sentence as IL6 in open-access papers (continued):
Sharing a sentence is not in itself a finding about the gene and the disease.
tumor (continued). "Interleukin 6 (IL-6) (mainly of tumor origin) facilitates GSH release from hepatocytes and its interorgan transport through the blood circulation to growing metastatic foci in B16-F10-bearing mice." (PMID 24802641, 2014). "Our lab has shown that locally heating tumours at 43 °C for 30 min increases the intratumoural concentration of IL-6." (PMID 25430985, 2014). "Not only silencing of IL6 led to the reduction in the proliferation of tumor in co-culture experiments, but also bevacizumab administration reduced IL6 release itself from tumor microenvironment." (PMID 24885802, 2014). "The highest interleukin-6 concentration was detected in B16 tumor conditioned media, which also contained M-CSF." (PMID 25401795, 2014). "This tumor produced several cytokines and chemokines, including G-CSF, IL-6, and IL-8, resulting in several systemic responses and a rapidly growing tumor surrounded by inflammatory cells." (PMID 25123545, 2014). "It is also worth noting previously determined significant correlations between serum levels of TGFA and interleukin-6, circadian patterns in wrist activity and serum cortisol, as well as tumour-related symptoms in patients with metastatic colorectal cancer." (PMID 25278152, 2014). "In an IL‐6 secreting tumor model, there was increased glycogen breakdown, which showed that IL‐6 has a direct effect on glycogen metabolism in the liver." (PMID 24997069, 2014). "Tumor necrosis factor (TNF) and IL-6 were identified as mast cell chemoattractants, which in turn can result in enhanced tumor invasion and metastasis." (PMID 24978438, 2014). "Cases had a 9.4-fold higher expression of IL-6 compared to controls (p < 0.05), confirming the inflammatory nature of the tumor." (PMID 24872837, 2014). "ERneg BCSCs also expressed less IL-6 than ERneg tumor, but similarity of expression between 112 T tumor and BCSCs precluded significance." (PMID 25269750, 2014). "The extract at the dose 10 mg/kg inhibited the tumour growth by 69 %, increasing the release of IL-2, IL-6, and IFN-γ." (PMID 28324460, 2014). "Both SDF-1 and IL-6 can activate the androgen receptor (AR) at low levels of androgens in PCa cells and contribute to tumor progression to the castration resistant stage." (PMID 24664419, 2014). "On the other hand, the mice group on CRD exhibited the least tumor burden associated with a significant reduction in levels of insulin, IGF-1, leptin, MCP-1, VEGF and IL-6." (PMID 25026276, 2014). "Numerous studies have suggested that circulating IL-6 secreted from tumor cells plays an important role in cancer-induced cachexia." (PMID 25477992, 2014). "Those which have been found to suppress tumor growth include IL-2, IL-12, IL-13 and IFN (gamma, beta and alpha) while IL-4, IL-6, IL-8 and IL-10 predominantly contribute to tumor growth." (PMID 24997057, 2014). "In conclusion, the results of our study suggest that low-dose irradiation of tumor beds can induce IL-17A production via IL-6 and TGF-β production, and promote the growth of subsequently implanted tumors." (PMID 25181290, 2014). "IL-6 is produced by tumor and stromal cells and contributes to tumorigenesis by various mechanisms, including angiogenesis, cell survival and metastasis." (PMID 25490767, 2014). "IL-6 was reported to enhance PCa cell proliferation and protect cells from apoptosis in tumor xenografts." (PMID 24664419, 2014). "To explore the mechanisms involved in the inhibition of tumor growth mediated by the silencing of endothelial cell-IL-6, we analyzed tumor cell proliferation and intratumoral microvessel density by immunohistochemistry." (PMID 24533454, 2014). "Interleukin-6 (IL-6) is another key factor in the tumor microenvironment, which is involved in tumorigenesis and progression." (PMID 24789104, 2014).
tumor (continued). "NF-κB can also promote the secretion of interleukin 6 by adhesion with extracellular matrix proteins and bone marrow stromal cells, initiating various signal transduction pathways and promoting tumor cell proliferation and drug resistance." (PMID 25289094, 2014). "IL-6, as an important proinflammatory cytokine, has been reported to be involved in both the tumor initiation and the promotion stages." (PMID 25093140, 2014). "These genes, together with STAT3 and IL-6, mediate chronic inflammatory responses in the tumor microenvironment, thus promoting survival of malignant cells." (PMID 24498382, 2014). "These SOCS3-deficient macrophages produce less IL-6 and TNF-α upon stimulation with tumor lysates due to aberrant STAT3 activity, again showing a positive link of SOCS and macrophage polarization." (PMID 25120543, 2014). "Previous studies have shown that MVD, VEGF and IL-6 are closely related to tumor proliferation and metastasis." (PMID 25238261, 2014). "As a matter of fact, in this model, the gender differences in tumor incidence are dependent on the estrogen-regulated difference in IL-6 production by male versus female KCs." (PMID 24723924, 2014). "Inflammatory mediators like Hmgb1, IL-23, and IL17 can promote tumor growth by activating IL-6/STAT3 pathway in a mouse model of melanoma." (PMID 24901008, 2014). "The interleukin-6 (IL-6) family of cytokines is at the forefront of the debate over the role of inflammatory cytokines in tumor suppression or progression." (PMID 24675570, 2014). "In obesity and DM, tremendous amount of the tumor-promoting cytokines IL-6 and TNF-α are produced, which is thought to promote HCC development." (PMID 24918094, 2014). "Mice were sacrificed after induction for 14, 16, 18, and 22 weeks for the examination of tumor burden, inflammation degree, and protein level of NF-κB and IL-6 in bowel tissues." (PMID 25093140, 2014). "In the present study, IL6 genotype predicted disease-free survival only among patients with ER-negative tumours, unless the patients had received chemotherapy." (PMID 25305747, 2014). "In CRC patients, IL-6 levels were significantly higher than these levels in healthy controls and were correlated with tumor stage, tumor size, liver metastasis and poor survival." (PMID 25322805, 2014). "ROS production by MDSC is sustained by the inflammatory tumor microenvironment, enriched, among others, in IL-10, IL-6, and TGF-beta, as well as by the cell-to-cell contact with lymphocytes." (PMID 25538892, 2014). "More intriguingly, by skewing macrophages polarization away from the M1- to a tumor-promoting M2-like phenotype, hypoxia and IL-6 cooperate to enhance the LLC metastasis both in vitro and in vivo." (PMID 25313135, 2014). "IL-6 levels were slightly increased in the tumor-draining lymph nodes of the pre-irradiated group, compared to control." (PMID 25181290, 2014). "TGF-β and IL-6 induce differentiation of CD4+ T cells into CD4+IL-17+ Th17 cells, which secrete IL-17 and IL-6 involved in inflammation and tumor development." (PMID 24949077, 2014). "Whilst there is clear evidence that IL-10 is immunosuppressive and protumorigenic, there is also new contradictory evidence that IL-10 can enhance apoptosis and downregulate VEGF, TNF-α, and IL6 production by TAMs to suppress angiogenesis and tumor growth." (PMID 24955376, 2014). "Murine and human mature adipocytes co-cultured with tumor cells exhibited changes of the number and size of lipid droplets, a decrease of adipose markers level and over-expression of IL6, leading to a more aggressive tumor behavior." (PMID 25089245, 2014). "We also found that CD4 T cells isolated from both tumor types have an increase in mRNA for IL-6 compared to peripheral blood CD4 T cells." (PMID 25436113, 2014).
tumor (continued). "LL-37 enhances MSCs secretion of IL-1β, IL-6, IL-8, IL-10 and TNFα while diminishing the secretion of IL-12, with a positive impact on tumor growth." (PMID 25303976, 2014). "In tumor-bearing state, G-CSF and IL-6 cooperated to enhance the potential of neutrophils to express Bv8 and MMP-9, and decrease the ability of neutrophils to release TRAIL, MPO and NE." (PMID 25587026, 2014). "Here, we challenged this paradigm and observed that endothelial cell IL-6 levels have a direct impact on tumor cell phenotype and tumor growth in vivo." (PMID 24533454, 2014). "Consistent to the roles of SDF-1 and IL-6 in enhancing tumor cell mobility, we observed that CM from PR positive cells inhibited not only PCa cell migration, but also invasion." (PMID 24664419, 2014). "For example, hypoxia (HIF1α), epithelial-mesenchymal transition, inflammatory cytokines (e.g., IL-6 and TGFβ), and embryonic microenvironments can all promote the reprogramming of CCs and increase the overall stemness of the tumor." (PMID 24955094, 2014). "In conclusion, the present pilot study revealed a significant correlation between three serological markers (osteopontin, IL-4 and IL-6) and a histopathologically confirmed neoplasm of the head and neck." (PMID 25120668, 2014). "Transfecting IL-17 into hepatocellular carcinoma cells significantly promotes neoangiogenesis, neutrophils recruitment, and tumor growth via AKT-dependent IL-6/JAK2/STAT3 signaling pathway in vivo." (PMID 24382972, 2013). "Data obtained from cell and xenograft tumor growth experiments revealed that inhibiting IL-6 resulted in slower tumor growth and reduced invasiveness." (PMID 23561329, 2013). "On the other hand, when overexpressed in organs such as the liver, brain, or lung, IL-6 can promote metastasis by attracting and promoting tumor cells." (PMID 23552194, 2013). "The expression levels of IL-6 and IL-8 have been found to be elevated in the tumor, saliva, and serum of OSCC patients compared to the control groups." (PMID 23762476, 2013). "Among the 173 EC tissues analysed, 88 (51%) showed positive IL6 immunoreactivity, and there was a positive correlation between IL6 overexpression and tumours developing locoregional or distant metastasis." (PMID 23837802, 2013). "IL-6 signaling can function as a regulator of tumor cell proliferation in cancer, while G-CSF is thought to promote tumor angiogenesis via increasing circulating endothelial progenitor cells and Gr1+CD11b+ cells in cancer animal models." (PMID 24278103, 2013). "The number of detectable tumors and maximal tumor diameters were also significantly smaller in IL-6−/− mice." (PMID 23593346, 2013). "STAT3 is found aberrantly activated, downstream of IL-6, in a number of chronic inflammatory conditions leading to tumour transformation or auto-immunity." (PMID 23460527, 2013). "In tumor cells, constitutive activation of STAT3 can be caused by abnormal and sustained autocrine and/or paracrine signaling including interleukin-6 (IL-6) signaling." (PMID 23658720, 2013). "Recent studies have reported that pro-inflammatory cytokines such as gro-α, interleukin 6 (IL-6) and interleukin 8 (IL-8) have the potential to modulate stroma and promote tumor growth." (PMID 24252539, 2013). "In fact, in the present study, inhibiting of IL-17A at tumor sites decreased IL-6 and CCL2 in tumors, and the migration of MDSCs in tumor tissues was obviously reduced." (PMID 23372655, 2013). "Prdm1, a transcriptional repressor and effector of Il-6 signaling, was also uniquely up-regulated in disseminated tumor cells, suggesting that active Il-6/Jak/Stat signaling occurs in this population." (PMID 23520493, 2013). "Important populations in all these pro-tumor processes are M2 macrophages, N2 neutrophils, regulatory T cells, and myeloid derived suppressor cells; the main effectors molecules are CSF-1, IL-6, metalloproteases, VEGF, PGE-2, TGF-β, and IL-10." (PMID 23577028, 2013).
tumor (continued). "It is likely that these second-level signaling defects also contribute to the lower tumor burden observed in Vav2−/−;Vav3−/− animals, since previous reports have shown that IL6-mediated signaling is essential for skin tumorigenesis." (PMID 23935450, 2013). "IL-6 is highly expressed in the tumor context of type-2 ovarian cancers, particularly in ascitic fluid, and its level correlates with poor prognosis." (PMID 24202339, 2013). "Both TNF-α and IL-1β, also found to be upregulated following PTT, can promote tumor growth by inducing IL-6 expression." (PMID 23935927, 2013). "The fraction induced tumor cell apoptosis in vitro, an activity related to IL-6 secretion by the tumor cells." (PMID 23552194, 2013). "We also found that the tumor size is correlated strongly with IL-6 and IL-10 levels (r = 0.925, P < 0.001; r = 0.821, P < 0.001), respectively.Conclusion." (PMID 27335826, 2013). "IL-6 is expressed by primary human ovarian surface epithelial cells and has been detected profoundly higher in tumor tissue, plasma and malignant ascites of ovarian cancer patients." (PMID 23593315, 2013). "In particular, the in vitro production of proinflammatory mediators, such as interleukin-6 (IL-6) and CCL2, was markedly downregulated by trabectedin in circulating monocytes, macrophages, and tumor-associated macrophages (TAM) from human tumors." (PMID 23401820, 2013). "This suggests that tumor microenvironment also plays an important role in activating IL-6/STAT3 pathway, which forms a vicious cycle to promote tumorigenesis and invasion." (PMID 24116074, 2013). "EMT6_IL-6 cancer cells grafted into the mammary fat pads of syngeneic recipients recruited more MDSCs to the spleen, liver, lung and primary tumor mass compared to the control empty vector-transfected EMT6 (EMT6_Con) cells." (PMID 24021059, 2013). "Interleukin-6, a multifunctional cytokine, contributes to tumor cell proliferation and differentiation." (PMID 23762858, 2013). "Cytokine production by tumor cells was suspected; both serum granulocyte colony-stimulating factor (117 pg/mL; normal: <57.5 pg/mL) and interleukin-6 (83.5 pg/mL; normal: <2.41 pg/mL) levels were high." (PMID 23710188, 2013). "We also revealed that cancer cells affect IL-6 production from stromal fibroblasts through IL-1 signaling and that IL-6 is important for tumor growth through STAT3 activation." (PMID 23593346, 2013). "Previous studies show that blockade of IL-6 signaling can inhibit tumor growth and increase drug sensitivity in mouse models." (PMID 24260500, 2013). "Accordingly, the links between IL-6, angiogenesis, and promotion of cancer in tumor-bearing mice were further investigated using a xenograft tumor model." (PMID 23561329, 2013). "In summary, IL-6 inhibition sensitizes tumor cells to irradiation, increasing cell death and DNA damage, and mitigates tumor regrowth after irradiation by eliminating RT-triggered MDSC infiltration and angiogenesis." (PMID 23806095, 2013). "The transwell invasion assays in HSC-3 and OC-3 cells suggested that the tumor cell invasiveness was restored by IL-6." (PMID 23762476, 2013). "Interleukin-6 (IL-6) mediated Stat3 activation is viewed as crucial for multiple tumor growth and progression." (PMID 24191246, 2013). "The P2Et fraction exerts its activity on the primary tumor, reduces cell migration to distant organs, and decreases IL-6 serum levels, implying tumor microenvironment mechanisms." (PMID 23552194, 2013). "Subsequently, The TAM will secrete growth factors such as EGF, TGFβ, FGF, VEGF, IL1, TNF and IL6 that promote tumor cell proliferation, invasion and metastasis." (PMID 23874655, 2013). "Since IL-6 is a known target gene of NFκB signaling, we examined if tumor enhancement mediated by IL-6 positive fibroblasts is NFκB dependent." (PMID 23593346, 2013). "As determined using clonogenic assays and delayed tumor growth, inhibition of IL-6 by transfection of an IL-6 silencing vector increased radiosensitivity." (PMID 23561329, 2013).
tumor (continued). "We examined growth and immune signalling proteins such as EGFR, HSPA8 and cytokines IL-6 that are involved in the survival of tumor." (PMID 23414419, 2013). "Functional assays suggest that IL-6 influences the ability of cancer cells to metastasize to distant sites and that IL-6 promotes tumor growth in a paracrine fashion in vivo." (PMID 24260500, 2013). "In HCC patients tumor size was correlated strongly with IL-6 and IL-10 levels (r = 0.925, P = 0.001; r = 0.821, P = 0.001), respectively." (PMID 27335826, 2013). "IL-6, a multi-functional cytokine, is the main activator of STAT3 signaling and the inducer for androgen receptor (AR) expression, STAT3 activation has been reported to mediate the radioresistance of tumor, and be up regulated by IL-6." (PMID 23806095, 2013). "Within the tumor microenvironment, IL-6 binds to gp80/gp130, leading to Janus kinase (JAK) activation and phosphorylation of Stat3, which regulates the expression of genes that mediate cellular proliferation and prevent apoptosis." (PMID 24062985, 2013). "KrasG12D; IL-6-/- mice exhibited increased tumorigenesis, but slower tumor growth and longer survival, than KrasG12D mice." (PMID 24260500, 2013). "It was also seen that P276-00 treatment reduced expression of tumor micro-environment proteins such as IL-6, secreted EGFR and HSPA8." (PMID 23414419, 2013). "ELISA data revealed that IL-6 silencing vector clearly attenuated IL-6 secretion in cell culture supernatants and serum from mice after 28 days of tumor implantation." (PMID 23637926, 2013). "DEN-induced tumors share similar pathogenesis, in which pro-inflammatory cytokines such as IL-6 and TNFα promote tumor development." (PMID 24339898, 2013). "To assess the contribution of IL-6 signaling inhibition on tumor progression and survival time in vivo, we crossed IL-6-/- mice with mutant KrasG12D mice because IL-6 is a downstream effector of oncogenic Ras to promote tumorigenesis." (PMID 24260500, 2013). "IL-6 is a significant mediator of the inflammatory response and involved in tumor angiogenesis and tumorigenesis." (PMID 23985826, 2013). "IL-6 is not only upregulated in tumor cells but—together with its target, C-reactive protein (CRP)—present at elevated levels in the sera of WM patients." (PMID 24106612, 2013). "Exercising mice showed a 38% decrease in mitotic cell/caspase 3 positive tumor cell ratio and featured a reduced increase of IL-6." (PMID 23731674, 2013). "Tumor IL-6 expression and circulating IL-6 levels decreased in all groups as compared to controls, whereas hepatic GSH levels increased." (PMID 23517603, 2013). "In the tumor cell lysates, we found that the curcumin significantly reduced IL-6 levels compared to the saline group." (PMID 24156030, 2013). "Tsai and colleagues demonstrated that secretion of IL-6 by MSCs activated the signal transducer and activator of transcription-3 pathway in cancer cells and promoted tumor formation." (PMID 23763837, 2013). "Strikingly, after exposure of the tumor-bearing mice to MF, the levels of IL-6, G-CSF and KC were decreased, while IL-12 was increased." (PMID 24278103, 2013). "Even single dose of minocycline was effective at significantly lowering plasma and tumor IL-6 levels." (PMID 23593315, 2013). "As for macrophages in a tumor microenvironment, our previous study showed that miR-155 regulated inflammatory cytokine production, including IL-6, in TSN-exposed monocytes via targeting C/EBPβ." (PMID 24194900, 2013). "IL-6 can promote tumor cell proliferation in several tumor cell lines, including human cervical carcinomas mediated cachexia." (PMID 24376459, 2013). "Some cytokines, such as IL-6 and IL-8, are essential for maintenance of senescence but at high levels, these factors can contribute to tumour progression." (PMID 23180582, 2013). "Diagnosis of a tumor that produced granulocyte colony-stimulating factor and interleukin-6 was established." (PMID 23710188, 2013).